ZNF3 (zinc finger protein 3)
Description:
Involved in cell differentiation and/or proliferation.
Synonyms: KOX25; A8-51; PP838; FLJ20216; HF.12; Zfp113
Tractability: PROTAC: UniProt records ubiquitination sites on it; ubiquitination databases record sites on it.
Gene: Protein-coding gene on chromosome 7 (100,064,033 to 100,082,703, reverse strand). Ensembl gene ENSG00000166526.
Subcellular location: Nucleus
Subcellular location (Human Protein Atlas): Nucleoplasm
Pathways (Reactome):
Gene expression (Transcription): Generic Transcription Pathway
Gene Ontology:
Molecular function: identical protein binding; protein binding; DNA binding; DNA-binding transcription factor activity, RNA polymerase II-specific; RNA polymerase II transcription regulatory region sequence-specific DNA binding; zinc ion binding
Biological process: leukocyte activation; regulation of transcription by RNA polymerase II; regulation of DNA-templated transcription
Cellular component: nucleus
Genetic constraint (gnomAD): Loss-of-function variants: 17 observed, 38.87 expected, observed/expected ratio (o/e) 0.44, 90% interval 0.3 to 0.66. The upper end of that interval is the gene's LOEUF score, 0.66, which puts it in group 2 of 6, group 1 being the genes least tolerant of losing a copy. Missense variants: 462 observed, 569.92 expected, observed/expected ratio (o/e) 0.81, 90% interval 0.75 to 0.88. Synonymous variants: 201 observed, 210.53 expected, observed/expected ratio (o/e) 0.95, 90% interval 0.85 to 1.07.
Homologues: Orthologues: rabbit ZNF3 (93% identical), chimpanzee ZNF3 (92% identical), pig ZNF3 (92% identical), macaque ZNF3 (91% identical), guinea pig ZNF3 (89% identical). Paralogues in human: ZNF189 (49% identical), ZNF33B (49% identical), ZNF658 (49% identical), ZNF879 (49% identical), ZNF135 (49% identical), ZNF568 (49% identical), ZNF585B (49% identical), ZNF7 (48% identical), ZNF182 (48% identical), ZNF429 (48% identical), ZNF311 (48% identical), ZNF30 (48% identical), and 164 more.
Diseases named in the same sentence as ZNF3 in open-access papers:
ZNF3 is named in the same sentence as 10 diseases in open-access papers, as found by Europe PMC text mining. Sharing a sentence is not in itself a finding about the gene and the disease. The quoted sentences say what the papers report.
lung carcinoma (2 papers, 2024 to 2025). "ZnF3 from AC induces apoptosis in lung cancer cells and activates macrophages via the AKT/mTOR pathway." (PMID 40141325, 2025). "ZNF3 and BZW2 have not been previously related with IBD pathogenesis, and both were identified as common overregulated genes in colon and lung cancer, respectively, suggesting their importance in the establishment of tumoral processes." (PMID 39791702, 2024).
Alzheimer disease (1 paper, 2014). A progressive, neurodegenerative disease characterized by loss of function and death of nerve cells in several areas of the brain leading to loss of cognitive function such as memory and language. "We also report ZNF3 gene on chromosome 7 and a cluster of genes on chromosome 11 (SPI1-MTCH2), showing gene-based genome-wide significant association with Alzheimer's disease." (PMID 24922517, 2014).
asthma (1 paper, 2020). "Chromosome 17q21 is an area of interest for asthma and contains a cluster of genes linked to asthma in several GWAS studies, including the GSDMB (Gasdermin B) and IKZF3 (Ikaros family zinc finger protein 3) genes." (PMID 33133517, 2020).
colon cancer (1 paper, 2024). "CD has no common overregulated genes with gastric cancer and one gene (TMTC4) and one TF (ZNF3) with colon cancer, located in the endoplasmic reticulum and membrane." (PMID 39791702, 2024).
Multiple myeloma (1 paper, 2020). "In Multiple myeloma, the continuous expression of Ikaros family zinc finger protein 1 (IKZF1) and Ikaros family zinc finger protein 3 (IKZF3) is essential for the proliferation and survival of the myeloma cells." (PMID 32591583, 2020).
tumor (2 papers, 2018 to 2019). "Of note, ZNF3, ZNF257, ZNF479 and ZNF493, which were found to be mutated in the PanTT26 tumour, also appeared to be mutated in the PanTT39 tumour specimen." (PMID 30377343, 2019).
cancer (1 paper, 2010). A tumor composed of atypical neoplastic, often pleomorphic cells that invade other tissues. "To date, none of the 6 other HRneg/Tneg signature genes not functionally linked to chemokine pathways (PRRG3, RFX7, MATN1, SSX3, HRBL, and ZNF3) has shown any reported association with cancer." (PMID 20946665, 2010).
ZNF3 also shares sentences with these, for which no sentence is quoted: breast carcinoma (3 papers); emphysema (1); gastric cancer (1).